IL6 (interleukin 6)
Diseases named in the same sentence as IL6 in open-access papers (continued):
Sharing a sentence is not in itself a finding about the gene and the disease.
tumor (continued). "The chronic inflammatory response induced by tumour cells further enhances the infiltration of neutrophils, further promoting tumour progression through the secretion of interleukin-2 (IL-2), IL-6, IL-10, tumour necrosis factor-alpha (TNF-α), and vascular endothelial growth factor (VEGF)." (PMID 38496751, 2024). "In this study, the tumour-promoting effects of the TAM-derived IL-6 could be abrogated in these models with the addition of the anti-IL-6-receptor therapeutic antibody, Tocilizumab." (PMID 39684877, 2024). "This study aimed to determine whether macrophages secrete tumor-associated factors, such as TNF-α and IL-6, when co-cultured with cancer cells treated with TiO2@OMV carriers and subjected to radiation therapy." (PMID 39728581, 2024). "In the TME, IL-6 is closely associated with tumorigenesis, EMT, and tumor metastasis." (PMID 38424624, 2024). "Moreover, the expressions of immune-suppressive cytokines TGFβ and IL6 were also inhibited in total tumor and CD45− cells, especially IL6." (PMID 39201460, 2024). "IL-6 might exert its biological actions as an autocrine and/or paracrine factor in the cardiac myxoma cells in a similar fashion as other human tumor cells." (PMID 38396907, 2024). "Given its important role in tumor progression, as well as the established correlation between high levels of serum IL-6 and shorter survival, IL-6 could be a prognostic biomarker for PCa patients." (PMID 39335188, 2024). "IL-6 is considered and oncogenic cytokine, similar to IL-1 and IL-8, and is reported to cause EMT, induce angiogenesis and tumor growth, disrupt cell–cell communication, impede macrophage function, and promote epithelial and endothelial cell migration and invasion." (PMID 38473882, 2024). "Additionally, increases in inflammatory cytokines, such as IL‐6, have been shown to upregulate PD‐L1 on tumor cells." (PMID 39300829, 2024). "IL-6 is a multifunctional cytokine that is abundant in the tumor microenvironment." (PMID 38881895, 2024). "Furthermore, IL-6 signaling plays a critical role in carcinogenesis, inhibition of antitumor immunity, and promotion of tumor dissemination in the tumor environment." (PMID 39139287, 2024). "IL-6 is a critical factor in promoting tumor development 32,33." (PMID 39440046, 2024). "At the same time, senescence of tumor cells can induce a senescence-associated secretory phenotype (SASP), leading to the secretion of pro-inflammatory cytokines such as IL-1, IL-6, IL-8, which triggers an immune response and promotes the clearance of tumor cells." (PMID 38887516, 2024). "CAFs also indirectly stimulate metastasis through their interactions with TAMs: several CAFs-released cytokines recruit TAMs, such as CCL2 and CCL5 (chemokine ligand 2/5), while IL-4 and IL-6 polarize TAMs toward the M2 phenotype, which supports tumor growth and metastasis." (PMID 39765634, 2024). "Moreover, recent investigations have discovered that combining alum sulfate with vesicular stomatitis virus, an oncolytic virus, can notably elevate the levels of IFN-γ and interleukin-6 (IL-6), thereby enhancing the response of tumor antigen-specific T cells." (PMID 38801637, 2024). "Our previous studies showed that anti-IL-6R antibodies potentially inhibited tumor growth and invasiveness in vitro and in vivo through interfering with IL-6 signaling transduction in IL-6R expressing CRC cell lines, including Erk-1/-2, STAT3 and AKT phosphorylation/activation." (PMID 38256960, 2024). "Furthermore, silibinin inhibits signaling of nuclear factor kappa B (NF-κB), a key factor to mediate the expression of tumor-promoting cytokines, such as interleukin 6 (IL-6) and tumor necrosis factor α (TNF-α)." (PMID 38966629, 2024). "Additionally, recent evidence suggests that IL-6 levels are altered after tumor surgery or during chemotherapy, possibly mirroring therapy responses and disease-related factors such as tumor size, recurrence, or stage." (PMID 39412695, 2024).
tumor (continued). "Thus, secretion of an inhibitor of IL-6 signaling by OSU13-treated cells is likely to limit tumor progression and promote antitumor immunity." (PMID 38900577, 2024). "IL‐6 is not only a key factor in the inflammatory pathway of RA, but can also act on different signalling pathways to affect the cell cycle, thereby inducing tumour production." (PMID 38961677, 2024). "For example, it may reduce CD8 + T cell aggregation and inhibit their cytotoxicity to tumor cells by secreting IL-6 and TGF-β48." (PMID 38326344, 2024). "Elevated serum CRP has been reported to be associated with various unfavorable prognostic factors, such as a larger tumor size, aggressive histopathological type, and high serum levels of interleukin-6, which plays a crucial role in tumor growth and chemoresistance." (PMID 39043707, 2024). "IL-6 also stimulates angiogenesis, which is crucial for tumor growth and metastasis." (PMID 38338683, 2024). "For example, M2 phenotype‐macrophages could secrete IL‐4, IL‐5 and IL‐6 to enhance angiogenesis, immunosuppression and matrix remodelling during tumour progression." (PMID 38680032, 2024). "IL‐6 plays pivotal roles in lymphocyte differentiation, tissue inflammation, and tumor progression." (PMID 37452653, 2024). "Additionally, pro-inflammatory cytokine IL-6 produced by the adipose tissue was higher correlated to levels within circulation and the tumor." (PMID 39525621, 2024). "Their effects on IL-6 and cytochrome C levels and tumor cell migration were investigated." (PMID 39610815, 2024). "Besides IL-12, the expression of cytokines such as TNF-α, IL1β and IL-6 is also critical for the activation of anti-tumour immune responses." (PMID 39487861, 2024). "SOX4 and IL-6 were highly expressed in the tumor stage lesion." (PMID 39963655, 2024). "Therefore, inhibiting the IL-6 pathway to suppress systemic inflammation or mitigate the impact of IL-6 on tumor and immune cells within the TME remains an attractive potential therapeutic target." (PMID 38672257, 2024). "These drugs, in combination with therapies aimed at neutralizing the T cell suppressive activities of IL-6, IL-9 and/or IL-10, may reasonably help reducing immune evasion of tumor cells, thereby ameliorating the clinical management of the disease." (PMID 39281678, 2024). "Furthermore, the CC genetic variant was associated with higher levels of IL-6 and viral load in all HBV patients, whereas the TT genotype was associated with larger tumor size." (PMID 39071840, 2024). "Tumor histological and molecular analysis demonstrated decreased expression of IL-6 and CXCLs and a decreased ratio of MDSCs to CD8+ T cells in the WT CDX simultaneously injected with the YAP1-Sh clones compared with the WT cell-derived tumors in separate mice." (PMID 39630608, 2024). "Subsequent analysis aimed to explore whether combining IL-6, IL-8, and tumor markers could enhance predictive power." (PMID 38774604, 2024). "IL-6, a pleiotropic cytokine, is produced by various immune cells (monocytes, macrophages, T and B lymphocytes), epithelial, fibroblast, glia, adipocytes, and tumor cells within the tumor microenvironment (TME)." (PMID 38799159, 2024). "With MSCs designed to trigger NIS expression in response to IL-6 promoter activation, a novel tumor-targeted gene therapy strategy for GBM may be possible." (PMID 39199662, 2024). "Effects of tumor characteristics on serum IL6 levels of patients (n = 43)." (PMID 38978990, 2024). "In addition to T cell immunity, there is evidence that some cytokines, especially those involved in adaptive immune responses (e.g., IFN-γ, IL-6) contribute to anti-tumor immunity." (PMID 38675217, 2024).
tumor (continued). "Moreover, the exist of tumor, increased level of IL-6, IL-10, and decreased lymphocyte subset counts correlated to a poor outcome." (PMID 38173531, 2024). "An increased NLR has the potential to induce neutrophilia owing to the presence of tumor granulocyte colony-stimulating factor, which in turn can expedite tumor progression and augment the concentration of cytokines in the plasma, such as interleukin-6 and tumor necrosis factor-α." (PMID 38623101, 2024). "Moreover, microorganisms can drive malignant progression at extra-mucosal sites via TLR5-dependent signals to increase the expression of systemic IL-6 and immunosuppressive γδ T cells to regulate tumor-promoting inflammation." (PMID 39926112, 2024). "Inflammatory mediators such as proinflammatory cytokines (e.g., interleukin‐6 IL‐6]) and catabolic factors (e.g., glucocorticoids), either derived from tumour‐immune system crosstalk or produced by the tumour itself, activate proteolytic systems and blunt protein synthesis, causing muscle wasting." (PMID 38572511, 2024). "Reduced the levels of IL-1β, IL-6 and tumour TNF-α in cerebral tissue." (PMID 38585461, 2024). "Interestingly, the production of PDAC-derived exosomes requires IL-6 induction, and the secretion of IL-6 by polarized macrophages promotes the expression of FGD5-AS1 in tumor cells, forming a positive feedback loop." (PMID 40458305, 2024). "In addition, the release of EVs and IL-6 from colon cancer cells could be mitigated by treating tumor cells with atractylenolide I (an EV biogenesis inhibitor by regulating the STAT3 pathway in tumor cells), and consequently attenuate weight loss in tumor-bearing mice." (PMID 39697630, 2024). "This could reflect the importance of IL-6 inhibition in the physiologic context of the intraperitoneal tumor environment." (PMID 38689325, 2024). "Also, vascular CAFs have been shown to actively interact with tumor cells via the pro-invasive IL6/IL6R axis, promoting cancer stemness and contributing to iCCA progression." (PMID 39410050, 2024). "IL-6 may be a malevolent player in anti-tumor immune response, since it may promote survival and proliferation of tumor cells and metastatic spread." (PMID 39512342, 2024). "Thus, MHV68 infection greatly enhanced both the mRNA (lung) and protein levels (lung, serum) of IL-6 in tumor-bearing mice." (PMID 39338937, 2024). "In case of absolute or functional ID, patients with existing tumor should be substituted with IV iron, as most of the time the immune system is stimulated with corresponding interleukin-6 and hepcidin production, blocking oral iron uptake and iron release from stores." (PMID 38240843, 2024). "IL-6 modulates PD-L1 in tumor cells as well as modulating inflammatory and immune responses." (PMID 38532022, 2024). "As such, STAT3 mediates induction of immunosuppressive tumor-derived factors, including IL-10, IL-6, VEGF, and TGFβ which, in a positive feedback loop, amplifies STAT3 activation, generating a pathway for immune evasion by tumors with constitutive STAT3 activation." (PMID 38339245, 2024). "Importantly, conditioned media from tumor cells cultured alone produced low amounts of IL-6, and IL-6 secretion from mesothelial cells was dependent on the Notch signaling, as demonstrated by the MRK-003 treatment." (PMID 38575576, 2024). "Similarly, intratumoral and circulating IL6 levels have been shown to correlate with increased tumor progression, worsening patient outcomes and the accumulation and activation of both MDSC and TAMs." (PMID 38108458, 2024). "Moreover, in HCC, TAMs express high levels of SLC40A1, a marker gene encoding ferroportin, which activates Toll-like receptor (TLR) stimulation to produce IL-1β, IL-6, and IL-23, thus shifting innate immunity processes toward tumor-favoring activity." (PMID 39766202, 2024).
tumor (continued). "IL-6 derived from M2 type macrophages activates the Janus kinase 2/signal transducer activator of the transcription 3 pathway, promoting angiogenesis and inflammation in tumor tissues and enhancing the invasion, proliferation, and survival of cancer cells." (PMID 38627864, 2024). "A correlation analysis was performed on the levels of 12 CKs in the patients’ serum and the degree of tumor differentiation, revealing a significant correlation between IL-1β (P ═ 0.008), IL-6 (P ═ 0.005), and IL-8 (P ═ 0.05) levels and the degree of tumor differentiation." (PMID 38920620, 2024). "Scholars have stated that kefir reduces tumor cell viability and growth rates, regulates cytokine expression in tumor tissues (e.g., downregulates IL-6, IL-10 and IL-1β, upregulates TNF-α, IL-10, and IL-4), promotes apoptosis, and exerts immune-enhancing effects." (PMID 39605907, 2024). "Moreover, mice transplanted with ART1-sh CT26 cells that had high levels of IL-6 displayed tumours with smaller volumes (P < 0.05)." (PMID 38504172, 2024). "Thus, this indicates the important role of both IL-6 and IL-4 in stimulating macrophage polarization in the tumor and finally increasing tumor aggressiveness." (PMID 39057050, 2024). "Other myokines like IL-6 and IL-15 contribute to tumor suppression by hindering adipogenesis, while IL-6, IL-10, and IL-8 can bolster immune cell activity, enhancing their numbers and cytotoxic capabilities, thereby fostering a “hot” immune microenvironment conducive to fighting cancer." (PMID 39346906, 2024). "This is of importance, as the previous animal studies that described tumor-stroma IL-6/STAT3 communication and reported the efficacy of the combined STAT3 and MEK inhibition to overcome immunotherapy resistance in PDAC did not report the sex of the animals used." (PMID 39684385, 2024). "We demonstrate that tumor-educated granulocytic leukocytes can manipulate tumor cell plasticity through OSM/IL-6/JAK signaling, promoting the emergence of a highly metastatic SCA1+ CSC population that is transcriptionally distinct from the endogenous SCA1+ CSC population." (PMID 38236642, 2024). "Within tumor cells, F. nucleatum induces pro-inflammatory signaling through the TNFα, NF-kB, and IL-6/IL-8 pathways and promotes tumor growth, EMT, metastasis, and therapy resistance, while also suppressing NK cell-mediated tumor cell killing and T cell infiltration into tumors." (PMID 39272898, 2024). "Beside Vpr, age, HIV viremia, HCV viremia, CRP, and IL-6 were also related with tumor occurrence." (PMID 38166062, 2024). "However, another recent study showed that high expression of IL6+ immune cells within the stroma and invasive front of CRC tumours was associated with favourable clinical characteristics and better survival outcomes in early-stage disease (n = 153)." (PMID 39766336, 2024). "IL-6 can also induce the production of M1 macrophages to generate an anti-tumor immune response." (PMID 38294629, 2024). "In CCA tumor tissues, the expression of IL-6 was positively correlated with gp130, JAK2, and STAT3." (PMID 38881895, 2024). "Likewise, P. crinita free extract (25, 50 mg/kg), revealed a notable decrease in the IL-6 gene expression (10%, and 20%, respectively) related to a tumor control group." (PMID 38469406, 2024). "Moreover, a positive correlation between IL‐6 expression and tumour‐infiltrating macrophages was observed in these samples." (PMID 37974543, 2024). "It is worth noting that TAMs-derived IL-6 actively participates in the interaction between tumor cells and macrophages and dramatically enhances the proliferation, invasion and migration of OSCC, which deserves further research and is expected to become a potential therapeutic target." (PMID 39877372, 2024). "However, this induction was clearly enhanced by the presence of tumor cells (tnfa, 17.3-fold increase; il1b, 30.3-fold increase; il6, 30.7-fold increase)." (PMID 39114912, 2024).
tumor (continued). "However, IL-6 expression was notably increased in the tumor tissues, suggesting an inflammatory response potentially contributing to the anti-tumor activity of GAS-NK cells." (PMID 39349746, 2024). "We further investigated whether the characteristics of tumor and locations of tumor would influence serum levels of IL-6." (PMID 38978990, 2024). "In addition, IL-6 increases PD-L1 and PD-L2 expression by cancer cells in various tumor microenvironments." (PMID 38726369, 2024). "Once activated, this transcription factor regulates the expression of cytokines and factors involved in cancer development and progression, such as IL-6 for tumor cell survival, the angiogenic factor VEGF, and IL-8, further producing mediators for immune cell recruitment." (PMID 39355131, 2024). "Similar to IL-6, IL-17 behaves paradoxically to tailor tumor cells during oncogenesis." (PMID 38279220, 2024). "Higher levels of IL-6 were reported in surrounding adipocytes when the tumor sizes were bigger." (PMID 39040042, 2024). "Furthermore, adipose tissue adjacent to a growing tumor secretes IL-6, confers the resistance to radiotherapy, and upregulates checkpoint effector kinase (Chk1) responsible for resistance to radiation therapy." (PMID 39040042, 2024). "Data suggest that under non-tumor conditions, IL-6 concentration is directly influenced by Vpr, but once tumors are developed, IL-6 is produced by multiple factors alongside Vpr, for example, inflammation or tissue damage that associated with tumor development." (PMID 38166062, 2024). "In cancer, IL-6 signalling promotes tumor growth, metastasis and immune evasion." (PMID 38689325, 2024). "Interleukin 6 (IL-6) is significantly enriched in the supernatant of cultured MSCs and exerts an immunosuppressive effect; however, other studies have shown that IL-6 can promote the expression of programmed death-ligand 1 to inhibit anti-tumor immunity." (PMID 38755705, 2024). "On the other hand, tumor cells secrete a variety of growth factors and cytokines, such as interleukin 6 (IL-6), tumor necrosis factor-α (TNF-α) and interferon-γ (IFN-γ), which may also lead to such results." (PMID 38180753, 2024). "In addition, it significantly inhibits the expression of NF-κB signaling dependent proinflammatory genes IL-6 and IL-1B through RAD51, thus blocking the STING-associated anti-tumor immunity in stromal tumor-infiltrating lymphocytes (sTILs)." (PMID 39638799, 2024). "Furthermore, tumor-produced factors including IL-6, TGF-β and CSF-1 can also induce the polarization of TAM towards the M2 phenotype." (PMID 39606239, 2024). "M1 macrophages express Type I cytokines with an anti-tumor effect, such as tumor necrosis factor-α (TNF-α), interferon-γ (IFN-γ), IL-6; M2 macrophages express Type II cytokines, which inhibit T cell-mediated anti-tumor response, such as IL-10, IL-13, transforming growth factor-β (TGF-β)." (PMID 39735340, 2024). "Furthermore, IL-6, CXCR4, CXCL8, and MMP-9 indicate higher diagnostic utility based on the AUC than the well-established tumor markers, such as CEA and SCC-Ag in OC patients." (PMID 38673838, 2024). "One of the effects of the release of IL-6 in the tumor is the activation of the STAT3 signaling pathway in malignant cells, altering cell-to-cell adhesions and promoting a number of cellular processes such as increased cell proliferation, enhanced motility and the activation of the EMT program." (PMID 38473317, 2024). "Additionally, IL-6 has been shown to recruit bone marrow-derived suppressor cells (MDSCs), which suppress the immune response to tumor antigens and inhibit T cells, including those involved in HCC." (PMID 38304429, 2024). "This may be attributed to the increased localized production of IL-6 around tumor cells, contributing to elevated IL-6 levels in saliva." (PMID 38803729, 2024). "IL6 is an inflammatory cytokine gene found in nearly all tumor microenvironments." (PMID 38032489, 2024).